TAGLN2P1 (transgelin 2 pseudogene 1)
Gene: Processed pseudogene on chromosome 8 (106,697,427 to 106,698,013, reverse strand). Ensembl gene ENSG00000253676.
Diseases named in the same sentence as TAGLN2P1 in open-access papers:
TAGLN2P1 is named in the same sentence as 1 disease in open-access papers, as found by Europe PMC text mining. Sharing a sentence is not in itself a finding about the gene and the disease.
TAGLN2P1 shares sentences with these, for which no sentence is quoted: tumor (1 paper).